FN1 (fibronectin 1)
Diseases named in the same sentence as FN1 in open-access papers (continued):
Sharing a sentence is not in itself a finding about the gene and the disease.
glioma (71 papers, 2003 to 2025). A benign or malignant brain and spinal cord tumor that arises from glial cells (astrocytes, oligodendrocytes, ependymal cells). "Our Kaplan–Meier analysis demonstrated that high expression of COL1A1, COL1A2, COL3A1, COL5A1, COL8A1, ELN, FN1 resulted in lower OS in all grade glioma patients, in turn causing poor prognosis." (PMID 36106447, 2022). "Our result indicates that both FN1 and IL-18 are significantly associated with poor prognosis of glioma patients (P-value <0.05)." (PMID 31118022, 2019). "FN1 has previously been implicated in cohesive invasion in glioma and gene knockdown increased cell-matrix adhesion." (PMID 27738329, 2016). "Moreover, the abundance of FN1 + TAMs hold promise for predicting immune therapy response and aiding in more precise risk stratification of recurrent glioma patients." (PMID 39375795, 2024). "Single-cell RNA (scRNA-seq) sequencing has revealed distinct TAM subpopulations, such as C1Q+ macrophages in hepatocellular carcinomas and FN1+ TAMs in gliomas, which define traditional classification and exhibit unique functional characteristics." (PMID 40850976, 2025). "Evidence from prior studies show that FN1 enhances glioma development by interacting with integrin b, and activating MMP2/MMP9 to accelerate the invasion and metastasis of cancer cells." (PMID 41199745, 2025). "In glioma, a macrophage subtype defined by high FN1 expression, termed FN1+ TAMs, has been shown to critically promote tumor recurrence." (PMID 41417432, 2025). "FN1 (Fibronectin 1) promotes glioma cell invasion and migration by interacting with integrin receptors, particularly α5β1, contributing to its role as a negative prognostic marker." (PMID 41356219, 2025). "Key hub genes such as TLN1, FN1, and IRF7 were associated with glioma progression and poor prognosis." (PMID 40365337, 2025). "Expression of FN1 was detectable in one of the serum‐cultured glioma cell lines (U87; 62.8 ng/mg of total protein), whereas U251, three GSC cultures, and primary M2 macrophages (n = 2) showed no detectable expression." (PMID 38705944, 2024). "Our results based on several patient‐derived GSC cultures indicate that FN1 expression in glioma cells is low." (PMID 38705944, 2024). "Earlier studies to identify differentially expressed genes in glioma revealed that FN1 is overexpressed in gliomas, compared to normal brain tissue." (PMID 35454889, 2022). "miR-1 expression markedly inhibits tumorigenicity and prolongs animal survival, and FN1 restoration in miR-1-expressing cells in turn restores tumorigenicity, which indicates the critical role of FN1 in glioma progression." (PMID 35954323, 2022). "Another report also indicated that FN1 can significantly modulate the progression of glioma cells by preserving integrin β1 FN receptors in glioma cells." (PMID 34093898, 2021). "FN1 affects proliferation, senescence and apoptosis of human glioma cells through PI3K-AKT signaling pathway." (PMID 34276798, 2021). "As for FN1, anaplastic astrocytoma and glioblastoma express this extracellular matrix protein at higher levels than low grade glioma." (PMID 34502484, 2021). "The FN1 gene acts as a regulator of glioma cell activity, and its suppression inhibits the cell proliferation and reduces migration and invasion that occurs through activation of the PI3K/AKT signaling pathway." (PMID 31396530, 2019). "Some studies have found that FN1 is the hub gene in glioma, a result that is consistent with our findings; as such, FN1 is a potential target for diagnosis and therapy." (PMID 28924174, 2017). "FN1, a downstream target and regulator of TGFB1, which plays a key role in matrix assembly was recently associated with glioma cell cohesion and motility, as well as tumour angiogenesis." (PMID 27049916, 2016). "Overexpression of RTVP-1 in A172 glioma cells induced a mesenchymal-like morphology, upregulated the mesenchymal markers fibronectin 1 (FN) and α-SMA and increased cell migration of these cells." (PMID 26267319, 2015).
glioma (continued). "Advances in single-cell technology have led to the discovery of multiple TAM subpopulations, such as thrombospondin-1+ (THBS-1+) macrophages in hepatocellular carcinoma and FN1+ TAMs in gliomas, each with unique transcriptional profiles and clinical significance." (PMID 40850976, 2025). "Furthermore, FN1 was highly expressed in high‐grade gliomas and was its expression level was negatively correlated with GBM prognosis." (PMID 39640361, 2024). "Interestingly, most of these proteins are ECM molecules and contribute to the invasiveness of glioma cells, including FN1, TNC, LAMC1, COL1A1, EGFR, CDK6, and COL6A2." (PMID 37059730, 2023). "GBM also had higher FN1 expression than low-grade gliomas (P < 0.001)." (PMID 36856115, 2023). "FN1 and its receptor α5β1 integrin also contribute to the tumorigenesis of glioma." (PMID 37059730, 2023). "In addition, FN1 is involved in the maintenance of the FN1 receptor integrin β1, inducing immunosuppression and promoting progression in glioma." (PMID 36151071, 2022). "Our results showed that FN1, ITGA5, OSMR, and NGFR were overexpressed in TCGA-GBM, suggesting that these genes were not only prognostic but also diagnostic between high-grade gliomas and normal brain tissue." (PMID 35954323, 2022). "Moreover, NOX2 increases the expression of mesenchymal-subtype-related genes, including COL5A1 and FN1 in U87MG glioma cells." (PMID 35158782, 2022). "A recent study showed that FN1 gene expression was higher in glioma tissues than in normal tissues." (PMID 34026352, 2021). "Our patient GBM cell models offer alternative ways to study the effect of FN1 protein level and matrix deposition on FN1 functions in glioma signaling events that promote tumor proliferation, EMT, migration/tissue invasion/metastasis, survival, and treatment resistance." (PMID 34502484, 2021). "Moreover, the expressions of SERPINE1 and FN1 were highly correlated among the high-grade gliomas (correlation coefficient r = 0.687), suggesting the activation of TGFβ pathway." (PMID 19192267, 2009). "Additionally, FN1 + TAMs were found to contribute to the regulation of an immunosuppressive microenvironment in gliomas, and their abundance might serve as an indicator of patients' sensitivity to immunotherapy." (PMID 39375795, 2024). "Moreover, they suggest the involvement of the FAP+ pericyte‐like cells in the secretion of essential basement membrane proteins, which together with COLI and FN1 may create a permissive environment for glioma cell dissemination." (PMID 38705944, 2024). "Here, we detailed the highly altered proteins (COL1A1, FN1, VTN, etc.)and the phosphosite (FN1_T1642) in the extracellular matrix (ECM) of BrM, as compared to primary brain tumor gliomas." (PMID 39716938, 2025). "Next, we interrogated the glioma cohorts from TCGA and CGGA databases to further examine the expression and correlation characteristics of RUNX1, FOSL2, FN1, COL4A1, and LUM in GBM tumorigenesis." (PMID 38286983, 2024). "Immunohistochemistry (IHC) staining revealed that the expression level of collagen IV was significantly higher in GBM than low‐grade glioma (LGG), with similar trends observed for FN1." (PMID 39640361, 2024). "We identify FAP+ pericyte‐like cells as the main producers of ECM rich in COLI and FN1 in GBM and provide evidence that this ECM facilitates migration and adhesion of glioma cells through FAK activation." (PMID 38705944, 2024). "Subsequently, we further analyzed the previous transcriptome sequencing data and found that silencing PRMT6 in glioma cells can reduce the expression of invasion-related molecules (TGFB1/2, MMP3/9/14, FN1, ROCK2, etc.)." (PMID 39043634, 2024). "FN1 is a key substrate interacting with FAM20C and was also reported to promote migration and invasion of glioma cells." (PMID 36825005, 2023). "Based on further validation using the Chinese Glioma Genome Atlas (CGGA) database, we identified FN1, ITGA5, OSMR, and NGFR as stiffness-dependent prognostic genes." (PMID 35954323, 2022).
glioma (continued). "Four stiffness-dependent prognostic genes (FN1, ITGA5, OSMR, and NGFR) were identified from GSE158097 and TCGA glioma datasets using bioinformatics analysis." (PMID 35954323, 2022). "After validation using the Chinese Glioma Genome Atlas (CGGA) database, we further identified four stiffness-dependent prognostic genes: FN1, ITGA5, OSMR, and NGFR." (PMID 35954323, 2022). "Distinct proteins have been identified in different glioma subtypes, including YKL40, fibronectin 1 (FN1), EGFR, and Stat3." (PMID 35436989, 2022). "FN1, COL1A1, COL6A1, and LTBP1 were significantly expressed in GBM compared with WHO grade II and III glioma." (PMID 34638384, 2021). "The type A and B gene expression patterns, arranged by the correlation to FN1-expression, were also observed among Cancer cell line encyclopedia (CCLE) glioma cell lines and The cancer genome atlas (TCGA) glioblastoma samples." (PMID 34021259, 2021). "Of the genes identified in the bulk RNA-seq analysis, only FN1, CDH2, and CDH11 were expressed in the glioma single-cell RNA-seq data, so we also visualized VIM as a post-EMT marker and SFRP1 as a pre-EMT marker." (PMID 33319914, 2020). "The function of fibronectin 1 (FN1), cyclin A2 (CCNA2), and cyclin B2 (CCNB2) in glioma OS has been reported." (PMID 32642801, 2020). "Survival analysis showed that the expressions of S100A4, FN1, and MMP-2 were negatively correlated to over-survival significantly in GBM and Brain Lower Grade Glioma." (PMID 33004792, 2020). "Specifically, LSM2 depletion resulted in the upregulation of extracellular matrix (ECM) genes like FN1 and COL1A1, which could disrupt tumour cell-ECM interactions and potentially diminish the invasive phenotypes of glioma cells." (PMID 40365337, 2025). "In addition, ESURATAG-GS expression positively correlates with protein expression of tumor aggressiveness marker, Snail and FN1, confirming the role of ESURATAG-GS in tumor progression in gliomas." (PMID 40718795, 2025). "A negative correlation was observed between the abundance of FN1 + TAMs in primary gliomas and the interval time to recurrence, suggesting poor prognosis for glioma patients with high levels of FN1 + TAMs." (PMID 39375795, 2024). "Also, HSP47 can stimulate glioma stem cell (GSC) stemness survival by upregulating angiogenesis and ECM restructuring genes (CD44, LAMC1m, Col4A2, ITGB1, FN1, and MMP9) for GSC reactivation, migration, and invasion through a TGF-β and CD44 signaling pathway." (PMID 38994941, 2024). "In addition to COLI and FN1, several other ECM proteins were more abundant in the 3D extracellular matrices produced by FAP+ pericyte‐like cells compared to glioma cells." (PMID 38705944, 2024). "Compared to U87 glioma cells, FAP+ pericyte‐like cells and HBVP had 15–44 times higher abundance of collagen alpha‐1(I) chain, 16–31 times higher abundance of collagen alpha‐2(I) chain proteins, and 21–68 times higher abundance of FN1." (PMID 38705944, 2024). "Moreover, a more differentiated phenotype is observed in glioma stem-like cells exposed to FN1, with decreased levels of SOX2 and increased levels of GFAP, highlighting the importance of FN1 for glioma onset and progression." (PMID 35562862, 2022). "In addition, we found that the high‐risk group exhibited a significantly higher expression level of FN1 and VIM, which indicated glioma in this group was easier to migrate and invade." (PMID 36070228, 2022). "Similarly, the expression levels of key mesenchymal molecules including YKL40/CHI3L1 and FN1 (FIBRONECTIN 1) in GICs can be greatly induced by TNF-α treatment or overexpressing C/EBPβ, a transcription factor essential in mesenchymal transformation of gliomas." (PMID 27259253, 2016). "In glioma tissues of GBM, mesenchymal subtype cells have the high expression of mesenchymal subtype signature genes, including chitinase 3 like 1 (CHI3L1), collagen type V alpha 1 chain (COL5A1), fibronectin 1 (FN1), cyclin B1 (CCNB1), and maternal embryonic leucine zipper kinase (MELK)." (PMID 35158782, 2022).
glioma (continued). "However, only FN1 was overexpressed in TCGA-LGG, implying that FN1 could be an early detection biomarker for low-grade glioma patients." (PMID 35954323, 2022). "Finally, by using gene correlation analysis, we found that the COL1A1, COL1A2, FN1, ITGA1, ITGB1, and ANXA1 genes may play a synergistic role in glioma patients." (PMID 35711921, 2022).
melanoma (71 papers, 1995 to 2026). A malignant, usually aggressive tumor composed of atypical, neoplastic melanocytes. "Melanocytes upregulated FN1, an extracellular vesicle protein with antiapoptotic functions, linked to a mesenchymal melanoma phenotype and poor prognosis in CM and UM." (PMID 40311102, 2025). "Ectopic WT-Bmal1 and dHLH-Bmal1 increased genes associated with mesenchymal melanoma state, such as Sox9, Fn1, Col1a1, Prrx2, Klf4, Snai2, Twist2, Lmo1 and Axl31." (PMID 38245503, 2024). "Furthermore, melanoma cells with FN1 expression are strongly associated with a pro-survival MITFlow state, upregulation of ZEB1 and hypoxia." (PMID 33870460, 2021). "For instance, the extracellular matrix protein fibronectin (FN1) contained an additional exon that was preferentially detected in Rs but skipped in NRs, both in melanoma and BC." (PMID 41273175, 2025). "FN1 is upregulated in the metastatic niche when lung as well as melanoma cell lines are implanted in lung." (PMID 38546390, 2024). "One previous study demonstrated that SNA coupled with the p65 subunit of NF-κB and PARP1 bound to the FN1 promoter at proximal (−236/+72) region to activate FN1 transcription in melanoma cells." (PMID 34571852, 2021). "The ECM remodeling molecule fibronectin-1 (FN1) is increasingly expressed not only on melanoma cells compared to benign nevi but also on metastatic versus primary melanoma." (PMID 33870460, 2021). "For instance, FN1 is upregulated in the metastatic niche when lung as well as melanoma cell lines are implanted in lung." (PMID 33731188, 2021). "Just as FN1, glypican-6 is upregulated in melanoma cells versus melanocytes and in metastatic versus primary melanoma." (PMID 33870460, 2021). "Later findings supported this work, as Li and others demonstrated that small interfering RNA (siRNA)-mediated downregulation of FN1 suppress the migration, invasion, adhesion, proliferation capabilities, and induced apoptosis of melanoma cells." (PMID 34858485, 2021). "In a Ncr1 KO murine model, there was increased metastasis caused by decreased Ncr1-regulated production of both TNFα and IFN-γ, the latter also directly decreased the ECM protein fibronectin 1 (FN1) in both melanoma and lung adenocarcinoma models." (PMID 33499238, 2021). "A specific protein profile was discovered for each cell line, e.g., EGFR in OSCC, Muc5AC in PDAC, and FN1 in melanoma vesicles." (PMID 32886718, 2020). "This cooperativity was partly dependent on cell‐derived FN1, which protects melanoma cells from anoikis (Boisvert‐Adamo & Aplin, 2006) and appears to provide a survival advantage for melanoma cells independent of their phenotype." (PMID 32145051, 2020). "Recently, Glasner and colleagues showed that natural killer cell-mediated IFN-γ production led to the increased expression of FN1 and resulted in decreased metastasis formation in melanoma." (PMID 30736807, 2019). "A similar observation had been made using antibodies specific to individual domains of FN1, which also detected the occurrence of matrix remodelling during melanoma progression." (PMID 29545604, 2018). "FN1 is also one of the genes overexpressed both in primary melanomas compared to benign nevi (2.2-fold) and in metastatic compared to non-metastatic primary melanomas (2.0-fold)." (PMID 26918341, 2016). "Determining if these changes are associated with the formation of tubular FN1-, COL-I-, and tenascin C-containing fibrillar structures, which we have previously suggested to be invasion channels for melanoma cells, remains of interest." (PMID 26918341, 2016). "We further compared the Kaplan-Meier survival rates of patients with primary melanomas showing low and high FN1 mRNA expression levels and found the survival times to differ highly significantly between patient groups." (PMID 26918341, 2016).